METTL21EP (methyltransferase like 21E, pseudogene)
Description:
Protein-lysine methyltransferase.
Synonyms: METTL21CP1
Gene: Protein-coding gene on chromosome 13 (102,880,040 to 102,896,033, forward strand). Ensembl gene ENSG00000250878.
Homologues: Orthologues: chimpanzee METTL21EP (91% identical), rabbit METTL21EP (84% identical), rat Mettl21e (82% identical), dog METTL21EP (81% identical), mouse Mettl21e (81% identical), guinea pig METTL21EP (80% identical), pig METTL21EP (79% identical), macaque METTL21EP (58% identical), tropical clawed frog mettl21e (55% identical), zebrafish mettl21e (49% identical). Paralogues in human: METTL21C (43% identical), EEF1AKMT3 (31% identical), METTL21A (30% identical), VCPKMT (25% identical), METTL23 (20% identical).
Diseases named in the same sentence as METTL21EP in open-access papers:
METTL21EP is named in the same sentence as 1 disease in open-access papers, as found by Europe PMC text mining. Sharing a sentence is not in itself a finding about the gene and the disease.
METTL21EP shares sentences with these, for which no sentence is quoted: myopathy (1 paper).